SLC1A5 (solute carrier family 1 member 5)
Diseases named in the same sentence as SLC1A5 in open-access papers (continued):
Sharing a sentence is not in itself a finding about the gene and the disease.
tumor (continued). "The upregulation of ATF4-dependent expression of SLC1A5 and its splice variants eventually increase glutamine and tryptophan uptake that are highly demanded for rapid amino acids synthesis in tumor cells." (PMID 33330446, 2020). "While high SLC1A5 expression is associated with tumor progression and reduced overall survival in patients with ccRCC, the functional role of SLC1A5 in the growth and survival of ccRCC cells remains largely unknown." (PMID 40532011, 2025). "Furthermore, dysregulation of SLC1A5 is associated with tumor growth and with increased resistance to apoptosis." (PMID 40362545, 2025). "Similar associations with SLC1A5 mRNA were observed with high SLC1A5 protein expression, including larger tumour size, high tumour grade, high pleomorphism, high mitotic count, less tubular formation, poor NPI and the presence of lymphovascular invasion (P < 0.001)." (PMID 39843491, 2025). "High SLC1A5 expression levels could facilitate tumor proliferation and antioxidant capacity and are associated with poor prognosis and the ability to resist dasatinib, sunitinib, sorafenib, and imatinib treatment in several malignancies." (PMID 39223142, 2024). "GPT2 and SLC1A5 inhibitors may inhibit tumour growth and distant metastasis, and increase susceptibility to 5-fu and L-OHP therapy." (PMID 37829798, 2023). "Alanine, Serine, Cysteine Transporter 2 (ASCT2), encoded by SLC1A5, mediates a Na+-dependent exchange of glutamine, which is known to drive the growth and proliferation of tumor cells, in the antiport of serine, threonine or asparagine, with a questionable role for cysteine as a substrate." (PMID 36839686, 2023). "Next, we found a close correlation between SLC1A5 and tumor-associated macrophages." (PMID 37566748, 2023). "In addition, univariate and multivariate Cox regression analyses showed that SLC1A5 expression (HR < 1) was a protective factor, while age (HR > 1) and tumor stage (HR > 1) were risk factors." (PMID 35305616, 2022). "Some previous studies have shown that SLC1A5 may cause ferroptosis of tumor cells, but the correlation between SLC1A5 and immune infiltration in GC is still largely unknown." (PMID 35835721, 2022). "SLC1A5 is highly associated with the infiltration of tumor immune cells." (PMID 36263042, 2022). "Furthermore, SLC1A5 was found to be related to immune response and SLC1A5 knockdown decreased the infiltration and M2 polarization of tumor-associated macrophages." (PMID 36566214, 2022). "Current studies on SLC1A5 in tumor cells have shown that increased SLC1A5 expression promotes glutamine dependence and antioxidant stress, affects the components of immune cell infiltration, and is associated with poor tumor prognosis." (PMID 35501667, 2022). "The association of SLC1A5 with immune cell infiltration and polarization had also been demonstrated and targeting SLC1A5 could be a potential strategy to strengthen anti-tumor immunity in previous studies." (PMID 36566214, 2022). "Additionally, SLC1A5 protein expression was associated with TN tumours (P < 0.001)." (PMID 39843491, 2025). "Since complicated cross-talk of death programs exist in cells, this study also identifies the concordant appearance of apoptosis, autophagy and ferroptosis, which may underlie the decreased viability in tumor cells following the SLC1A5 knockdown or cisplatin treatment." (PMID 39223142, 2024). "The ferroptosis-related gene SLC1A5 in the ceRNA network was associated with both tumor-infiltrating immune cells and immune checkpoints in the tumor microenvironment, suggesting that SLC1A5 may be a novel prognostic marker and a potential target for STAD immunotherapy in the future." (PMID 35305616, 2022). "miR-4652-3p suppressed glutamine metabolism in NSCLC cells by negatively regulating the MYC/SLC1A5 axis, consequently inhibiting cell growth and tumor progression in a xenograft mouse model, an effect reversed by MYC or SLC1A5 overexpression." (PMID 41654992, 2026).
tumor (continued). "For HCC, SLC1A5 expression is widely upregulated, and its high expression is significantly correlated with tumor growth, metastasis, and poor patient prognosis." (PMID 41293169, 2025). "When investigating the expression of SLC1A5 mRNA in molecular subtypes, high SLC1A5 mRNA expression tended to be associated with high BCSS in luminal B tumours (P = 0.094)." (PMID 39843491, 2025). "CD133 + GSCs also stabilize the stem cell phenotype and promote tumor initiation through the CD133-Akt-SLC1A5 signaling axis." (PMID 41201287, 2025). "SLC1A5 protein expression in the IHC-defined molecular subtypes was significantly lower in the luminal A tumours than in the other subtypes (P < 0.001)." (PMID 39843491, 2025). "Tumor suppressor miR-137 belongs to a class of small non-coding RNAs that block translation and promote degradation of SLC1A5 mRNA by targeting SLC1A5 mRNA, resulting in increased SLC1A5 expression and enhanced glutamine metabolism." (PMID 39973065, 2025). "For example, the blockade of SLC1A5 (ASCT2) impaired glutamine uptake and suppressed tumor growth by disrupting energy production and inducing apoptosis." (PMID 40282424, 2025). "Tumor cells and tumor-infiltrating myeloid cells have been observed to compete for glutamine uptake via the transporter protein SLC1A5." (PMID 40598593, 2025). "Although inhibition of SLC1A5 has shown some anti-tumor effects in vitro and in mouse models, safe and effective specific inhibitory drugs are still lacking and require further development." (PMID 39973065, 2025). "Among these, SLC1A4 and SLC1A5 are key transporters of neutral amino acids and are frequently upregulated in tumours, correlating with poor prognosis." (PMID 40660426, 2025). "High SLC1A5 mRNA expression was significantly associated with ER-negative, PR-negative, and HER2-positive tumours together with TN tumours (all P < 0.01)." (PMID 39843491, 2025). "Glutamine is a nutrient used by tumor cells, and the uptake of glutamine depends on the expression levels of glutamine transporters SLC1A5 or SLC38A1 on the cell membrane." (PMID 40075587, 2025). "In the bc-GenExMiner validation dataset, high SLC1A5 mRNA was predictive of poor OS in patients with luminal A tumours only (P = 0.025)." (PMID 39843491, 2025). "In this study, we have shown that SLC1A5, which is a primary transporter for Gln uptake, is highly expressed in a subset of ER + tumours that have high proliferation, i.e., luminal B tumours, and is related to poor patient outcome in this group." (PMID 39843491, 2025). "Animal experiments further confirmed that curcumin triggered GSH depletion and iron overload by promoting SLC1A5 overexpression in tumor tissues." (PMID 41515171, 2025). "Genetic or pharmacological inhibition of GLS1 or SLC1A5 significantly suppresses tumor growth in vivo." (PMID 39747079, 2025). "Considering the elevated expression of PHGDH, SLC1A5 and SLC38A2 in CRC and their association with tumour proliferation, metastasis and patient prognosis, we selected these genes for validation in real‐world patient cohorts." (PMID 40660426, 2025). "High SLC1A5 protein expression was significantly associated with ER-negative, PR-negative and HER2-positive tumours (P < 0.001)." (PMID 39843491, 2025). "It was demonstrated that blocking SLC1A5 greatly hindered tumor growth and migration in a subcutaneous xenograft model with renal carcinoma cells." (PMID 40723225, 2025). "In TME, tumor cells preferentially uptake Gln from the microenvironment for energy metabolism through the overexpression of SLC1A5 and SLC7A5 Gln transporters, thereby forcing NK cells into a metabolic crisis." (PMID 40959206, 2025). "SLC1A5 modulates tumor phenotypes and immune profile, and it exhibits tremendous potential to become a therapeutic target in future HNSCC/OSCC treatment." (PMID 39223142, 2024). "Tumor growth in vivo can be inhibited by neutralizing IL-23A with antibodies or by knocking down SLC1A5 gene expression." (PMID 39223142, 2024).
tumor (continued). "Solute carrier family 1 member 5 is a key protein responsible for glutamine transport, and its upregulation in tumor tissues indicates increased glutamine uptake." (PMID 38384814, 2024). "Inhibition of glutamine uptake by SLC1A5/ASCT2 inhibitor V-9302 additionally induces a marked reduction of tumor growth in vivo, which is accompanied by enhanced activation and functionality of effector T cells." (PMID 39211039, 2024). "It is worth noting that the CDKN1A gene, which encodes the protein p21 and plays critical roles in DNA damage repair, cell cycle inhibition, and tumor suppression, was significantly upregulated in the FaDu-sh-SLC1A5 group." (PMID 39223142, 2024). "High expression of SLC1A5 has been found in many tumor cells and is related to tumor growth proliferation and survival." (PMID 38791327, 2024). "TNBC patient tumours exhibited strong membrane expression of ASCT2 on 154/155 TNBC samples, in accordance with previous SLC1A5 (ASCT2) mRNA expression data on 96 patients in this same cohort." (PMID 39420093, 2024). "Upregulated ATF4 and SLC1A5 expressions are observed in tumor tissue, which is positively correlated with the tumor, node, and metastasis (TNM) stages." (PMID 39696988, 2024). "Our results suggest that folate metabolism- and glutamine metabolism-related genes, especially SLC1A5 and MTHFD2, are associated with KIRC prognosis, tumor stage, and lymph node metastasis status." (PMID 39958609, 2024). "Researchers have developed a variety of drugs targeting SLC1A5, an essential glutamine transporter protein in tumour cells." (PMID 38172980, 2024). "Third, to determine the impact of COL1 on the survival of tumor‐bearing mice, GSCs expressing control shRNA or SLC1A5 shRNA either alone or in combination with COL1 were implanted into the mice brains." (PMID 37997289, 2024). "Taken together, these results suggest that Silibinin represses GBM tumor growth by inhibiting the YY1/SLC1A5 pathway." (PMID 38410123, 2024). "In hypoxic tumor cells, it was demonstrated that Carbonic anhydrase IX interacts with SLC1A5 to maintain redox homeostasis through the GSH/GPX4 axis." (PMID 38705513, 2024). "In contrast, CsA alone or combined with CB-839 have minor effects on NRF2, KLF5, and SLC1A5 proteins derived from WT-201 tumor samples." (PMID 38830868, 2024). "Among them, there is solute carrier family 1, where protein 5 (SLC1A5/ASCT2) is the most frequently overexpressed transporter protein in the different human tumor cells dependent on extracellular glutamine." (PMID 39125992, 2024). "In the glutamine metabolic pathway, glutamine enters tumor cells through SLC1A5, where it is converted into glutamate by glutaminase and then enters the mitochondria." (PMID 38904011, 2024). "Folate and glutamine metabolism-related genes, especially SLC1A5 and MTHFD2, were associated with the prognosis, tumor stage, and lymph node metastasis status in KIRC." (PMID 39958609, 2024). "To gain insight into the influences of SLC1A5 on the tumor microenvironment and immune profile, we analyzed RNA sequencing data of 30 normal tissues, 55 OSCC tissues, and TCGA-HNSCC datasets using the Cibersortx algorithm." (PMID 39223142, 2024). "The role of glutamine transporter SLC1A5 in tumor progression and transarterial chemoembolization (TACE) efficacy is under study." (PMID 38844930, 2024). "SLC1A5 is an essential transporter for glutamine uptake, and SLC1A5-mediated glutamine transport plays a key role in tumor cell metabolism, proliferation, and ferroptosis." (PMID 37773303, 2024). "Notable among the candidate proteins was the neutral amino acid transporter SLC1A5 (ASCT2), the primary glutamine transporter in tumor cells." (PMID 38641063, 2024). "Conversely to SLC38A3, upregulation of SLC38A1, SLC7A6, and SLC1A5 transporters in HCC tumors was associated with decreased overall patient survival, with SLC1A5 being the most significantly associated with tumor aggressiveness." (PMID 39062801, 2024).
tumor (continued). "We now report that ABCG2 interacts with SLC1A5, a member of the human solute transporter superfamily and the major glutamine transporter in tumor cells." (PMID 38641063, 2024). "Similar to HIF-1α, HIF-2α can induce the expression of SLC38A2, SNAT2, SLC1A5 variant, GLS1, and SLC7A5, which can facilitate the rapid growth of tumor cells." (PMID 38172980, 2024). "Knockdown of the glutamine transporter ASCT2/SLC1A5 can dramatically reduce proliferation in vitro and tumour growth in xenograft models of TNBC." (PMID 39420093, 2024). "Our comprehensive study of glutamine transporters expression levels in HCC as well as their respective involvement in patient overall prognosis identified SLC1A5 as being an upregulated glutamine transporter specifically in aggressive HCC tumor subtypes." (PMID 39062801, 2024). "A study has shown that SLC1A5 inhibition in PC-3 cells reduces glutamine uptake, oxygen consumption, and fatty acid synthesis and suppresses tumor growth and metastasis; however, α-ketoglutarate addition reduces these effects of SLC1A5 inhibition." (PMID 37773303, 2024). "Then, the relationship between SLC1A5 expression and the tumor immune microenvironment was analyzed by single-cell analysis, gene set enrichment analysis (GSEA), and Tumor Immune Estimation Resource (TIMER)." (PMID 37566748, 2023). "SRCC increase glutamine uptake and metabolism by upregulating GPT2 and SLC1A5, leading to tumour resistance and malignant progression." (PMID 37829798, 2023). "The researchers showed through luciferase-binding experiments that MYC binds to the SLC1A5 promoter to initiate SLC1A5 transcription and promote glutamine uptake, to finally achieve tumour metastasis." (PMID 37829798, 2023). "Tumour cells achieve high intracellular concentrations of glutamine primarily through the upregulation of glutamine transporters, including ASCT2 (alanine, serine, cysteine transporter 2 or SLC1A5)." (PMID 37241864, 2023). "Among SLC family members, alanine-serine-cysteine transporter 2 (ASCT2, encoded by the SLC1A5) is recognised as the principal glutamine transporter and is critical for glutamine uptake in tumour cells." (PMID 37894450, 2023). "SLC1A5 expression is also upregulated in a highly tumorigenic subpopulation of tumor cells known as tumor-repopulating cells." (PMID 37545500, 2023). "The results showed that the expression levels of SLC1A5 were higher in tumor cell lines than in normal cells." (PMID 37566748, 2023). "To gain insight into the major cell types expressing SLC1A5 in the tumor microenvironment, we performed single-cell analysis of SLC1A5 expression in 79 tumor single-cell databases." (PMID 37566748, 2023). "In HCC patients, SLC1A5 expression is significantly elevated in tumor tissues, compared with corresponding normal tissues." (PMID 36902506, 2023). "They found that circ-LDLRAD3 controls SLC1A5 via sponging miR-137 in non-small cell lung cancer cells, controlling tumor cell apoptosis, migration, and proliferation." (PMID 37161350, 2023). "Relevant research on the preclinical drug V-2, which targets SLC1A5, has provided strong evidence that inhibiting SLC1A5 can effectively suppress tumor cell proliferation." (PMID 37566748, 2023). "In vivo study showed that overexpressing NEDD4L also significantly inhibited tumor growth, suppressed tumor cell proliferation, and inhibited the expressions of GLS1 and SLC1A5 in tumor tissue." (PMID 35593463, 2022). "Preclinical models have shown that pharmacological blockade of SLC1A5-dependent glutamine transport can exert anti-tumor effects." (PMID 35501667, 2022). "SLC1A5-mediated glutamine transport plays a crucial role in tumor cell metabolism, proliferation, and ferroptosis; therefore, inhibiting SLC1A5 and thus blocking glutamine transport is one of the approaches to treat solid tumors." (PMID 35305616, 2022).
tumor (continued). "Glutamine plays a pivotal role in the energy metabolism, survival, and growth of tumor cells, and higher levels of solute carrier family 1 member 5 (SLC1A5), a glutamine transporter, is expressed in tumor cells." (PMID 35527284, 2022). "The effects of SLC1A5 on the tumor immune microenvironment were analyzed by the CIBERSORT algorithm, ssGSEA method, and TISIDB and TIMER databases." (PMID 35419359, 2022). "At the same time, the potential biological function of differentially expressed ferroptosis-related genes was identified, and it was found that SLC1A5 was closely related to tumor immunity." (PMID 35835721, 2022). "Apart from that, increased hsa_miR-370-3p resulted in a significant suppression in cell proliferation, while increased SLC1A5 reversed these impacts in tumor cells." (PMID 36273140, 2022). "By detecting SLC1A5 mRNA expression, we confirmed that SLC1A5 expression was upregulated in NSCLC tumor tissues." (PMID 36192755, 2022). "In the tumor tissues of sh-circ_0000808 group, we found that circ_0000808 and SLC1A5 expression was enhanced, while miR-1827 expression was decreased." (PMID 36192755, 2022). "The CIBERSORT database and Spearman correlation analysis indicated that SLC1A5 was correlated with eight types of tumor-infiltrating immune cells and immune checkpoints, including PD-L1(CD-274) and PD-1(PDCD1)." (PMID 35305616, 2022). "IHC staining results showed that the SLC1A5-positive cells were increased in NSCLC tumor tissues compared to adjacent normal tissues." (PMID 36192755, 2022). "Nevertheless, studies on the role of SLC1A5 in immune cells, which play a key role in suppressing tumor growth, are only beginning." (PMID 35305616, 2022). "The expression correlation between SLC1A5 and immune cell marker genes suggested that SLC1A5 can regulate tumor immunity of GC through a variety of immune cell populations." (PMID 35835721, 2022). "Simultaneously, glutamine consumption, α-ketoglutarate production, and glutamate production were inhibited by downregulation of SLC1A5 in tumor cells." (PMID 36273140, 2022). "V-9302, an inhibitor targeting SLC1A5, significantly inhibits tumor cells proliferation in vitro, and suppresses tumor growth in mouse models, and also modulates the anti-tumor immune response." (PMID 35897036, 2022). "In NSCLC tumor tissues and cells, we also found the significantly overexpressed SLC1A5 at the protein level." (PMID 36192755, 2022). "In GBM, SLC1A5 expression is under the control of pro-oncogenic c-Myc protein but how this transporter supports the tumour cells proliferation and growth remain poorly understood." (PMID 34301218, 2021). "In contrast to 18F-FDG, 4-(18F)Fluoro-Gln uptake by tumor cells positively correlates with SLC1A5 expression." (PMID 33401748, 2021). "Inhibition of SLC1A5 can enhance the anti-tumor effect of Almonertinib in NSCLC both in vitro and in vivo (Graphical Abstract Image)." (PMID 34054543, 2021). "ASCT2, also known as SLC1A5, promotes the uptake of circulating glutamine into proliferating tumor cells." (PMID 33401672, 2021). "In this study, SLC1A5 inhibition not only enhanced the anti-tumor effect of Almonertinib on EGFR mutant cell lines (H1975), but greatly improved the anti-tumor effect of Almonertinib on EGFR WT cell lines (A549)." (PMID 34054543, 2021). "The main objectives of this study were to visualize the prognostic landscape of SLC1A5 in multiple cancers and determine the relations between SLC1A5 expression and tumor immunity." (PMID 34367941, 2021). "The 17 types of the total 24 tumor types in the TCGA dataset showed significantly higher expression of SLC1A5 than their normal counterparts." (PMID 34367941, 2021). "The second-highest correlation was found between SLC1A5 expression and CD86, a marker gene of tumor-associated macrophages with the ability to capture PD1-targeting antibodies on its surface and consequently limiting immunotherapeutic efficacy." (PMID 34367941, 2021).